CD4 (CD4 molecule)
Diseases named in the same sentence as CD4 in open-access papers (continued):
Sharing a sentence is not in itself a finding about the gene and the disease.
infection (continued). "In particular, it would be interesting to examine the role of these CD4 T cells in early infection and determine whether they are associated with the early development of nAbs in those who clear the infection." (PMID 31300682, 2019). "Interestingly, when we looked at polyfunctional CD4+ T cells we observed a significant increase in their frequency at 8 weeks post-infection in SV/129 mice compared to the susceptible murine models." (PMID 30881923, 2019). "Infection with HIV is associated with CD4 T cell depletion and dysfunction." (PMID 31497018, 2019). "The selection and retention of new CD4 alleles that block virus entry could protect a species from infection, at least until the virus population counter adapts." (PMID 31181085, 2019). "Resistance after this infection regime is dependent on CD4+ T cells and associated with Muc5ac production and an increase in intestinal epithelial cell turnover, confirming their importance even after this multi-infection regime." (PMID 31730667, 2019). "HIV-2 infection has been reported to be associated with slower disease progression as compared to HIV-1.However the data available with respect to immune activation associated with infection is limited, conflicting and has reported on either CD4 or CD8 compartment in isolation." (PMID 30744575, 2019). "In contrast, mac-tropic SIV is associated with CD4-independent infection via direct CCR5 binding." (PMID 30415390, 2019). "Also, both infections are associated with a progressive decline of CD4+T cells and loss of immune function, which manifests clinically as an increased susceptibility to opportunistic infections." (PMID 30744575, 2019). "In the multivariate analysis, anal mucosa infection by high-risk HPV was related to: CD4 nadir < 200 cells/uL (27.1% vs. 13.2%; OR 2.363, 95% CI: 1.062–5.256); and simultaneous infection by low-risk and high-risk genotypes (75.2% vs. 65.9%; OR 1.842, 95% CI: 1.015–3.344)." (PMID 31648254, 2019). "Interestingly, a recent study showed that CD4+ T-cell levels during the asymptomatic stage of infection was stronger associated with HIV-2 disease progression rate than with CD4+ T-cell decline." (PMID 31484562, 2019). "Previous work has shown that infected mice that are resistant (expel a high-dose infection) or susceptible (harbor a low-dose chronic infection) to T. muris infections make robust T. muris E/S-specific CD4+ T-helper (Th) cell recall responses and serum antibody responses." (PMID 31138806, 2019). "Several studies have also confirmed an association of TM infection with a lower CD4+ cell count." (PMID 31851879, 2019). "We additionally found that higher plasma sCD14 levels during the first year of infection were associated with higher viremia levels and lower CD4/CD8 ratios, immunological variables that at set point have been previously reported to be surrogates of disease progression and mortality." (PMID 31185037, 2019). "CD4-independent infection of CCR5+ cells may involve variants that have evolved a higher Env:CCR5 affinity." (PMID 30415390, 2019). "An important limitation to this would be ensuring the CD4 counts of potential recipients are within safe limits, as those who are severely immunosuppressed could increase their susceptibility to infection when undergoing spinal cord stimulation." (PMID 31249636, 2019). "Moreover, transcriptional profiling of viral-specific CD4+ T cells in LCMV clone 13 infection identified a loss in Th1 transcriptional signatures, as well as an enrichment of Tfh-associated transcripts." (PMID 30828337, 2019). "Additionally, deficiency in CD4+ T cells results in increased susceptibility to infection with Coccidioides." (PMID 31572393, 2019). "Rhesus macaques are often used in reservoir and cure studies as infection is associated with sustained viral loads, progressive CD4+ T cell depletion and chronic immune activation, and viremia can be controlled but not eliminated by cART, leading to viral rebound if cART is interrupted." (PMID 31297114, 2019).
infection (continued). "However, later post-infection, CD4+ T cell specific IL-4Rα-deficient mice and wild-type controls had equivalent parasite burdens in the spleen, liver and bone marrow as well as a similar hepatic granulomatous response." (PMID 31475014, 2019). "Hence, both CCR5- and CXCR4-tropic HIV-1 strains can cause CD4+ T cell depletion following infection via mucosal routes in a humanized mouse model." (PMID 30761146, 2019). "MHC-II genetic deficiency altering CD4+ T lymphocytes completely impairs Brucella control in lungs, liver and spleen, highlighting the crucial role of these cells in the development of a protective response against infection." (PMID 31572389, 2019). "Further studies are required to work out the mechanisms, but it is possible that these observations reflect reparative processes initiated by memory CD4 T cells that under conditions of acute infection are beneficial, but in this chronic model of infection become pathogenic." (PMID 30641955, 2019). "CycT1 was further upregulated in lymph node CD4 T cells, which may predispose many of these lymphoid cells for infection and latency generation." (PMID 30786885, 2019). "Additionally, starting ART shortly after infection has been a focus area, as this is associated with both a lower frequency of latently infected CD4+ T-cells in blood and tissue, and a better preserved T-cell function." (PMID 31484562, 2019). "Interestingly, the frequencies of HA-specific CD4+ T cells elicited by the quadrivalent VLP vaccine in this study were comparable to the levels associated with reduction of clinical signs of infection in children and adults." (PMID 31166987, 2019). "The endocytosed virus has been demonstrated to cause productive infection of CD4+ T cells." (PMID 31708924, 2019). "Our study suggested that there could be some other predictors of risk fractures in this specific population, such as infection-related factors: CD4+ cell count and the viral load." (PMID 31139152, 2019). "Most animals from both PRI-724-treated and control groups experienced a decrease in cell-associated SIV DNA in the different subsets of CD4+ T cells at weeks 27 to 28 compared to weeks 15 to 16 after infection, likely related to the expected reduction in virus persistence due to ART." (PMID 31619550, 2019). "Thus, the intriguing association between targeting CXCR6/CCR5 versus CCR5-only CD4+ T cell subsets and pathogenic infection outcomes in the HIV-1/SIVcpz/SIVmus/gsn/mon lineage requires further study." (PMID 29659623, 2018). "Several groups thus proposed that this cytopathic effect related to the formation of T-cell syncytia could be the mechanism of the CD4+ T cells loss observed during infection in HIV-1-infected patients." (PMID 29515578, 2018). "However, it has been demonstrated in vitro that immune activation can induce CD4 expression and thus susceptibility to infection." (PMID 29422894, 2018). "A CD4 lymphocyte count < 300/μL also indicates an increased risk for infection." (PMID 29325597, 2018). "To evaluate whether infection with the IN-deficient mutant was also able to trigger glycolysis, we infected CD4+ T cells with this HIV-1 mutant and analyzed their glycolytic activity." (PMID 30206166, 2018). "However, T cell depletion in outbred mice following Ft SchuS4 challenge demonstrated that sodB vaccinated outbred mice depleted of CD4+ T cells were highly susceptible to Ft SchuS4 infection with a MTD of 11 days." (PMID 30533047, 2018). "CD4 cells help to coordinate the immune system's response to certain microorganisms such as viruses; a low CD4 count is an indication of a higher risk of infection." (PMID 29546067, 2018). "However, CD4-depleted, Mincle-deficient mice were more susceptible to infection compared to their CD4-depleted wild-type counterparts." (PMID 29470553, 2018).
infection (continued). "Moreover, a higher proportion of these CD4+ T cells from PE243-infected mice produced IFNγ and in a lesser extent IL-17, while infection caused a reduction of CD4+ T cells producing IL-4." (PMID 30087337, 2018). "HIV infection results in the progressive depletion of CD4 T cells, the very cells that orchestrate the critically protective adaptive immune responses to pathogenic infections, until such time as the immune constitution is severely eroded and opportunistic infections ensue." (PMID 29614779, 2018). "By day 7 post-infection, the CD4+ T-cell populations in the wild-type and TLR3-deficient mice were 64.8% and 69%, respectively, which represented an increased frequency of CD4+ T-cells in the genital tract of wild-type and TLR3-/- mice was 38.2% and 46.8% over the mock controls." (PMID 29624589, 2018). "Although this patient has a lower HIV viral load and higher CD4 cell count (700 cells/mm3), the presence of these mutations may lead to a progression of infection." (PMID 29844604, 2018). "Conversely, increased Wnt and stem cell signatures, loss of epithelial differentiation, and exaggerated CD4+ T cell activation through increased antigen processing and presentation were specifically associated with the response to infection in susceptible mice." (PMID 29339782, 2018). "This suggests that induction, maintenance, and memory of the CD4 T cell response may be sensitive to the loss of antigen following antibiotic intervention during an infection." (PMID 30105030, 2018). "Because IFNγ/IL10 CD4 T-cell responses have been associated with high antigen burden in other systems, we assessed the relationship of Pf–specific responses and parasite density during the most recent infection (within 3 months prior to blood draw)." (PMID 29097996, 2017). "Nonetheless, a growing body of evidence indicates that CD4+ T cells can also exert a direct effector activity, which depends on intrinsic cytotoxic properties acquired and carried out along with the evolution of several pathogenic infections." (PMID 28289418, 2017). "Preferential infection of activated CD4 T cells may also explain sequential loss of CD4 T cells of defined specificities." (PMID 29250079, 2017). "We therefore hypothesized that HIV infection and pregnancy may act synergistically to impair cellular immunity, reducing CD4 counts and potentially increasing susceptibility to infection." (PMID 28382737, 2017). "Considering that neonates have fewer target CCR5+ T cells, and largely lack that hallmark CD4+ T cell depletion typical of adult infection, our attention turned toward studies on macrophages to better understand their contribution to exacerbated disease progression found in pediatric cases." (PMID 29259605, 2017). "Prior to secondary infection, normal mouse serum, immune serum, protein A-purified immune IgG, IgG-depleted serum, or Fab fragments were passively transferred to antibody-deficient (μMT) mice depleted of CD4+ T cells." (PMID 28739831, 2017). "Notably, pediatric cases of HIV/SIV exhibit faster and more severe disease progression than adults, yet neonates have fewer target T cells and generally lack the hallmark CD4+ T cell depletion typical of adult infections." (PMID 29259605, 2017). "For example, a highly pathogenic SHIV strain, SHIV-KS661, which has the env gene of HIV-1 89.6 and predominantly uses CXCR4 as the secondary receptor for infection, causes an infection that systemically depletes the CD4+ T-cells of rhesus macaques within 4 weeks following infection." (PMID 28431573, 2017). "In vitro, GC Tfh cells are more susceptible to infection with HIV‐1 than non‐GC Tfh cells or CXCR5− extrafollicular CD4+ T cells, and in vivo they have been shown to constitute the major CD4 T‐cell compartment for virus replication in both HIV‐1 172, 173 and SIV174, 175 infections." (PMID 28133804, 2017).
infection (continued). "Importantly, the permissive cell was identified before infection, thus revealing the biological basis of baseline CD4+ T cell susceptibility to HIV." (PMID 29073251, 2017). "Disturbances in CD4+ T-cell function most closely associate with the development of CM in humans, and thus the appropriate activation of T-cell responses is critical for containing infection." (PMID 29371497, 2017). "In IL-1RI−/− mice, C. neoformans 52D infection was associated with heightened lung eosinophilia, elevated airway mucus secretion, and a greater percentage of M2 macrophages and CD4+ Th2 cells along with significantly fewer lung neutrophils, DCs, Th1, and Th17 cells." (PMID 29403476, 2017). "Imbalances in the cytokine response favorable to infection with Schistosoma haematobium due to increased frequency of CD4+CD25hiFOXP3+ Treg, among other causes, might be modified by treatment with praziquantel." (PMID 28603524, 2017). "However, resolution of infection following L. major infection is primarily associated with CD4+ T cell-mediated immunity." (PMID 29167671, 2017). "As the participants with HIV infection in this sample had CD4 counts > 350 cells/mm3 at enrollment into the studies, it is unlikely that severe immunocompromise was responsible for the increased risk of dual-strain infection." (PMID 29281620, 2017). "This phenomenon also predicts that vaccination regimens that increase the pool of mucosal HIV-specific CD4 T cells may result in greater risk of virus acquisition consistent with the trend toward higher risk of infection among HIV vaccine recipients." (PMID 29250079, 2017). "The dynamics of latent HIV is linked to infection and clearance of resting memory CD4+ T cells." (PMID 29049331, 2017). "Another possibility is that GM-CSF-producing T cells are more abundant during the early stages of infection, as part of an initial Th17 response, and skewing toward a Th1 response may lead to the loss of GM-CSF production by CD4+ T cells." (PMID 29066547, 2017). "Compared to infection with the opal-containing parental virus, infection with the arginine mutant causes limited swelling and inflammation, as well as dampened recruitment of immune mediators of pathology, including CD4+ T cells and NK cells." (PMID 29138302, 2017). "The risk for infection is increased in aging and is marked by a CD4/CD8 ratio less than one." (PMID 28977399, 2017). "Associations between genetic variants in the MHC class II region and disease susceptibility imply that impaired antigen presentation or unstable MHC class II molecules contribute to insufficient CD4+ T-cell responses and, subsequently, to increased susceptibility to infections." (PMID 28449694, 2017). "Although it is still unclear whether IL-27 also regulates IL-10 expression by T cells during M. tuberculosis infection, IL-27Rα signaling in CD4+ T cells has been recently shown to confer susceptibility to this infection." (PMID 28584007, 2017). "Thus, relative CD4 expression levels correlated with susceptibility of HSPCs to infection by HIV-1 and HSPCs that express higher levels of CD4 are more likely to become infected." (PMID 28732051, 2017). "This loss in HA-specific CD4 T cell help was associated with a dramatic decline in HA-specific antibody, possibly due to limiting numbers of HA-specific CD4 follicular helper T cells following the secondary infection." (PMID 28493882, 2017). "Although type 1 immune responses characterized by the generation of Th1 CD4+ T cells are essential for viral clearance and the development of protective immunity during these infections, severity of illness is associated with type 2 polarization of the immune response." (PMID 28129374, 2017). "Mucosal infection with an M1 GAS strain induced a strong antigen-specific Th17 response in cells isolated from nasal-associated lymphoid tissue of C57BL/6 mice, with CD4+ cells producing IL-17A, whereas intravenous and subcutaneous infection produced IFN-γ secreting cells." (PMID 27241677, 2016).
infection (continued). "This simple CD4 genotyping method might be useful for selectively breeding CD4.A or CD4.B homozygous pigs and for developing association studies of immunity to infections and immunologically-related diseases." (PMID 27717346, 2016). "Because they are also membrane-associated, M1 and NA from infection or vaccines may be co-internalized with HA and CD4 T cells specific for these proteins may be able provide help, if these cells are contained within the CXCR5+CXCR3− pools." (PMID 26834750, 2016). "While progression of the infection is associated with a gradual loss of CD4 T-cells, the CD8 T-cell count (hereinafter referred to as CD8 count) is elevated at the very onset of infection and during the chronic phase until the late phase where major depletion of all T-cell subsets occurs." (PMID 26945343, 2016). "Whether, such additional mutations would further enhance Env: CD4 interactions or affect macrophage infection via a distinct mechanism is unclear." (PMID 27820858, 2016). "It appears, however, that marked immunosuppression, indicated by lower CD4 counts, may predispose subjects to infection with HEV." (PMID 27467394, 2016). "However, on day 2 post Pseudomonas aeruginosa wound inoculation, infection led to a significant loss of the CD4+, mCD4+, CD8+, mCD8+ cells in the spleen as compared to the sham mice (day 6)." (PMID 26859674, 2016). "Risk factors for increased vertical transmission of HIV were: injected drug use, confirmation of HIV infection in prenatal period or childbirth, non-use of antiretroviral drugs during pregnancy, high viral load, reduced CD4 T lymphocytes and presence of associated infections." (PMID 28076637, 2016). "These Env variants interact efficiently with low CD4 levels on macrophages for infection." (PMID 27820858, 2016). "In fact the persistent immune activation makes CD4 T cells more susceptible to infection and causes a vicious cycle increasing the production of soluble inflammatory markers such as IFN-γ, inflammatory cytokines (i.e. IL-6) and indoleamine 2,3-dioxygenase (IDO)." (PMID 27127532, 2016). "In our study, the CD38+ CD4+ T cells circulating during infection displayed a phenotype associated with recent activation and cytotoxic potential, suggesting that this cell population may be a subset of cytolytic CD4+ T cells." (PMID 27662621, 2016). "As such, considerable evidence suggests that CMV-specific CD4 + CD28null cell expansions are associated with systemic impairment and dysregulation of immune function leading to a heightened risk of infection and CVD, two of the leading causes of morbidity and mortality in AAV patients." (PMID 27450392, 2016). "We studied the role of HLA and KIR on risk of HIV acquisition and course of HIV viraemia and CD4+ T-cell counts through the first 5–10 years of infection in South African women infected with HIV-1 clade C in a nested case–control and prospective cohort study respectively." (PMID 26809736, 2016). "The profoundly depressed proportions of CD4+ splenocytes from Ctsl-/- mice at baseline and after infection may reflect generalized deficiency in development of CD4+ lymphocytes, with consequent impairment in early host defense." (PMID 27716790, 2016). "The lack of concordance between residual viremia and viral variants driving de novo infection of CD4+ T cells on ART, might also reflect the relative abundance of functional genomes, these being over-represented in the episomal pool." (PMID 27484989, 2016). "CD4+ T cells are critical in mounting an effective immune response to infections; hence, the decrease in local gut immunity due to a fall in CD4 T lymphocytes and the abnormality in their structure predispose the individual to the infection by intestinal pathogens." (PMID 27795876, 2016). "However, IL-27 impairs control of acute mouse hepatitis replication and associated pathology following infection of the CNS and this phenotype is associated with reduced accumulation of IL-10+ CD4+ T cells." (PMID 27926930, 2016).